TAC3 (tachykinin precursor 3)
Description:
Tachykinins are active peptides which excite neurons, evoke behavioral responses, are potent vasodilators and secretagogues, and contract (directly or indirectly) many smooth muscles. [Neurokinin-B]: Is a ligand for TACR3, and triggers G protein-coupled receptor signaling via activation of G(q) and phosphatidylinositol hydrolysis by phospholipase C. Binding to TACR3 also triggers signaling via activation of adenylate cyclase activity which results in increased intracellular levels of cyclic AMP (cAMP) (By similarity). Is a critical central regulator of gonadal function (By similarity).
Synonyms: NKB; NKNB; ZNEUROK1; NK3; LncZBTB39-1:2; LncZBTB39; HH10; PRO1155
Tractability: Small molecule: a high-quality ligand is known. Antibody: its Gene Ontology location is reachable by antibodies, with high confidence; UniProt places it where antibodies can reach, with medium confidence; UniProt predicts a signal peptide or a membrane-spanning region. PROTAC: a small molecule that binds it is known.
Target class: Secreted protein
Gene: Protein-coding gene on chromosome 12 (57,010,000 to 57,028,883, reverse strand). Ensembl gene ENSG00000166863.
Subcellular location: Secreted
Subcellular location (Human Protein Atlas): Vesicles; Predicted to be secreted
Pathways (Reactome):
Signal Transduction: G alpha (q) signalling events; Tachykinin receptors bind tachykinins
Gene Ontology:
Molecular function: protein binding; receptor ligand activity; signaling receptor binding
Biological process: phospholipase C-activating tachykinin receptor signaling pathway; adenylate cyclase-activating G protein-coupled receptor signaling pathway; female pregnancy; positive regulation of blood pressure; tachykinin receptor signaling pathway
Cellular component: extracellular region
Genetic constraint (gnomAD): Loss-of-function variants: 9 observed, 16.94 expected, observed/expected ratio (o/e) 0.53, 90% interval 0.32 to 0.93. The upper end of that interval is the gene's LOEUF score, 0.93, which puts it in group 3 of 6, group 1 being the genes least tolerant of losing a copy. Missense variants: 129 observed, 155.87 expected, observed/expected ratio (o/e) 0.83, 90% interval 0.72 to 0.96. Synonymous variants: 52 observed, 59.91 expected, observed/expected ratio (o/e) 0.87, 90% interval 0.69 to 1.09.
Homologues: Orthologues: chimpanzee TAC3 (99% identical), macaque TAC3 (92% identical), dog TAC3 (74% identical), guinea pig TAC3 (67% identical), pig TAC3 (66% identical), mouse Tac2 (64% identical), rat Tac3 (60% identical), tropical clawed frog tac3 (30% identical), zebrafish tac3a (22% identical).
Diseases named in the same sentence as TAC3 in open-access papers:
TAC3 is named in the same sentence as 64 diseases in open-access papers, as found by Europe PMC text mining. Sharing a sentence is not in itself a finding about the gene and the disease. The quoted sentences say what the papers report.
hypogonadotropic hypogonadism (33 papers, 2011 to 2025). Abnormal ovarian or testicular function due to insufficient hormonal stimulation from the hypothalamic-pituitary axis. "Inactivating mutations in Tac3 or TacR3 genes, encoding NKB and its receptor, respectively, have been demonstrated in patients suffering hypogonadotropic hypogonadism." (PMID 38516965, 2024). "Loss of function mutations in the gene encoding NKB (Tac3) and its receptor cause hypogonadotropic hypogonadism, suggesting that NKB has a stimulatory effect on the HPG axis." (PMID 35729637, 2022). "TAC3 has a role of a neurotransmitter, and it is well established that TAC3 mutations can lead to normosmic hypogonadotropic hypogonadism." (PMID 34630334, 2021). "Like kisspeptin, humans carrying loss-of-function mutations in neurokinin B [NKB; also known as tachykinin 3 (Tac3)] or in NKBR also display hypogonadotropic hypogonadism." (PMID 31354632, 2019). "Inactivating mutations of either Kiss1 (encoding kisspeptin) or Tac3 (encoding NKB) result in hypogonadotropic hypogonadism and pubertal failure in humans." (PMID 29302059, 2018). "Inactivating mutations of the genes encoding for NKB (TAC3) or the NKB receptor NK3 (TACR3) cause hypogonadotropic hypogonadism in the human." (PMID 24062728, 2013). "All these data strongly suggest that the gonadotrope deficiency in subjects with TAC3/TACR3 mutations is linked to a slowing of the frequency of endogenous GnRH secretion." (PMID 22031817, 2011). "In humans, the neuropeptides kisspeptin and neurokinin B (NKB) have been identified as major activators of pulsatile GnRH secretion, with loss-of-function mutations in KISS1 (encoding kisspeptin) and TAC3 (encoding NKB) genes associated with hypogonadotropic hypogonadism (HH)." (PMID 37092553, 2023). "It is known that mutations in the TAC3 or TACR3 genes, respectively coding for NKB or NK3R, cause hypogonadotropic hypogonadism in humans because of disturbances in the secretion of gonadotropic hormones from the anterior pituitary gland." (PMID 40552024, 2025). "In various species, including humans, inactivating mutations in KiSS-1R, TAC3 (NKB), or TACR3 (its receptor) lead to pubertal failure and hypogonadotropic hypogonadism." (PMID 40689179, 2025). "Supporting human reproductive biology, TAC3 has been identified in the bloodstream of patients with central pubertal disorders and hypogonadotropic hypogonadism." (PMID 36005579, 2022). "Similar to kisspeptin, the loss-of-function mutation in neurokinin B (NKB; also known as tachykinin 3 (Tac3)) or of its receptor (NKBR, Tac3R, NK3R) also exhibit hypogonadotropic hypogonadism in humans." (PMID 34681067, 2021). "The loss of function mutations in the genes encoding TAC3 or TACR3, whose translation products are NKB and its receptor, lead to hypogonadotrophic hypogonadism in humans." (PMID 31474940, 2019). "Its critical involvement in the regulation of human reproduction is well established by the hypogonadotropic hypogonadism of the TAC3- or TAC3R-mutant humans." (PMID 25713511, 2015). "Mutations in the TAC3 or TACR3 genes encoding for NKB and its receptor NK3R, respectively, lead to hypogonadotropic hypogonadism and infertility in humans." (PMID 25713511, 2015). "Patients with loss-of-function mutation in neurokinin B (TAC3) and its receptor (TAC3R) show hypogonadotropic hypogonadism characterized by failure to progress through puberty." (PMID 24615662, 2014). "Loss-of-function mutations of Tac3 and Tacr3, which encode NKB and NK3R, respectively, have been identified in patients with hypogonadotropic hypogonadism." (PMID 25362998, 2014). "Inactivating mutations in the genes encoding NKB (TAC3) and its cognate receptor, NK3R (TACR3), have also been recently shown, like GPR54 mutations, to result in hypogonadotropic hypogonadism; characterized by a failure to progress through puberty." (PMID 22377698, 2013).
hypogonadotropic hypogonadism (continued). "Mutations associated with loss of TAC3/TACR3 gene functions cause IHH (isolated hypogonadotropic hypogonadism), characterized by a lack of sexual maturation and low circulating levels of LH and gonadal steroids." (PMID 32189110, 2020). "NKB, encoded by the TAC3 gene in humans and Tac2 gene in rodents, acts via the NKB receptor (NK3R; encoded by TACR3 gene in humans and Tacr3 in rodents), and mutations in either TAC3 or TACR3 are associated with hypogonadotropic hypogonadism." (PMID 31382541, 2019). "Moreover, mutations in the TAC3 and TACR3 genes were found to cause hypogonadotropic hypogonadism in humans, demonstrating that NKB and NK3R play a key role in the regulation of reproduction." (PMID 31906206, 2019). "Mutations in the genes encoding for kisspeptin, NKB, and their receptors (KISS1, TAC3, KISS1R, TACR3) result in hypogonadotrophic hypogonadism, indicating that both kisspeptin and NKB are critical for normal GnRH secretion in humans and subsequent puberty and reproduction." (PMID 27379743, 2016). "Mutations of TAC3 are also quite rare causes of human XY DSD, with the OMIM database containing only a few reports of hypogonadotropic hypogonadism 10, with or without anosmia, caused by mutation of this gene (OMIM #614839)." (PMID 36280698, 2022).
Infertility (17 papers, 2013 to 2023). "In human patients with TAC3 gene mutations, a Thr for Met mutation in the “FXGLM” motif of NKB was known to cause hypogonadism or even infertility in adulthood." (PMID 34884698, 2021). "Indeed, human genetic studies have associated loss of function mutations on either TAC3 or TACR3 genes (encoding NKB and its receptor NK3R respectively) with hypogonadism and infertility, similar to the phenotypes of Kiss1 or GPR54 mutants." (PMID 23543285, 2013). "In this study, the GnRH1, GnRHR, KISS1, KISS1R, TAC3 and TAC3R genes were analyzed in two unrelated nIHH patients successfully treated for infertility." (PMID 27544332, 2016).
hypogonadism (7 papers, 2013 to 2022). A disorder characterized by decreased function of the gonads. "Another important aspect is the possible reversal of TACR3 and TAC3 mutation-related hypogonadism." (PMID 32508745, 2020). "Loss-of-function mutations in the tachykinin 3 (TAC3) gene, which encodes the stimulatory neuromodulator NKB, and tachykinin receptor 3 (TACR3), which encodes the NKB receptor, are associated with the development of hypogonadism and delayed puberty." (PMID 35328752, 2022). "The role of KNDY in humans is highlighted from the observations that loss-of-function mutations in the genes encoding for kisspeptin (KISS1), kisspeptin receptor (KISS1R), NKB (TAC3), or NKB receptor (TACR3) are associated with delayed puberty and hypogonadism." (PMID 31920956, 2019). "In humans, the role of KNDy system has been clarified by the association of loss-of-function mutations in the kisspeptin (KISS1), kisspeptin receptor (KISS1R), neurokinin B (TAC3), or neurokinin B receptor (TACR3) genes and delayed puberty and hypogonadism." (PMID 36619551, 2022).
polycystic ovary syndrome (7 papers, 2013 to 2024). A disorder that manifests as multiple cysts on the ovaries. "Recently, a reduced expression of TAC3 and TAC3R was observed in cumulus cells and mural granulosa cells from polycystic ovary syndrome (PCOS) patients." (PMID 34055685, 2021).
preeclampsia (7 papers, 2014 to 2022). Preeclampsia is a hypertensive disorder of pregnancy that is characterized by new-onset hypertension with proteinuria presenting after 20 weeks of gestation, and depending on mild or severe forms may initially present with severe headache, visual disturbances, and hyperreflexia. "The increased placental expression of TAC3 gene belongs to the mechanism responsible for the elevated circulating neurokinin B levels in preeclampsia." (PMID 27347521, 2015). "The particular ligand/receptor system NKB/NK3R, (encoded by TAC3/TACR3), previously investigated only for preeclampsia, alcohol, and cocaine dependence, gained an increasingly important role in human reproductive axis and in CHH onset in the last seven years." (PMID 25254043, 2014). "Additionally, this list included several genes associated with preeclampsia (PE) such as TIMP3, Wnt regulator DKK1, fibronectin FN1, cannabinoid receptor CNR1, neurokinin receptor TAC3, retinol binding protein RBP4, and prolactin PRL." (PMID 30131724, 2018). "In the placenta of preeclampsia women, elevated circulating NKB and increased tac3 expression are reported as compared with placenta of normal pregnant women." (PMID 36589829, 2022). "TAC3 and TACR3 may contribute to preeclampsia during late pregnancy." (PMID 36589829, 2022).
asthma (6 papers, 2011 to 2026). "TAC3 is linked to paucigranulocytic asthma and increased expression of metabolic and mitochondrial pathway genes, especially those for oxidative phosphorylation." (PMID 41303221, 2025). "Researchers tracked U-BIOPRED severe asthma patients for a year and found that 55% maintained stable endotypes (TACs), while 45% changed, mainly from TAC1 or TAC3 to TAC2." (PMID 41303221, 2025). "Among non-type 2 phenotypes (TAC2 and TAC3), TAC2 may principally include non-type 2 severe asthma possessing a mixed type 1/type 17 neutrophilic immune response in the background of the variable extent of eosinophilic type 2 immunity." (PMID 30736433, 2019).
Obesity (6 papers, 2017 to 2025). Accumulation of substantial excess body fat. "SIRT1 association to the Tac3 promoter decreased between late juvenile development and the completion of puberty, but neither obesity nor undernourishment altered this association." (PMID 30305620, 2018). "Among them, namely Tac1 encoding SP and NKA, Tac3 encoding NKB, and Tac4 encoding HK-1 or EKs, Tac1 encoding product SP plays an important role in a variety of physiological behaviors such as pain perception, neurogenic inflammation, smooth muscle contraction and obesity regulation." (PMID 38254396, 2024). "Especially interesting and promising target molecules for obesity-derived implications in placenta could be CCL2, PRL, MMP12, TAC3, PRG2 and IGFBP1 that were the most dysregulated genes among our study group." (PMID 28125591, 2017).
oral squamous cell carcinoma (3 papers, 2021 to 2025). "Tachykinin 3 (TAC3) has been shown to affect gingival oral squamous cell carcinoma cells possibly through tachykinin receptor 3 (TACR3) in bone matrix." (PMID 39790460, 2025). "Finally, TAC3, which was also observed to be inhibited in our experiment, has been found overexpressed in tumors such as oral squamous cell carcinoma and seems to play a key role in tumorigenesis." (PMID 34683922, 2021).
amenorrhea (1 paper, 2017). The absence of menses in a woman who has achieved reproductive age. "We examined adolescents and young adults with stalled puberty or unexplained amenorrhea for mutations in GNRHR, FGFR1, TAC3, and TACR3 genes." (PMID 29182666, 2017).
congenital hypogonadotropic hypogonadism (1 paper, 2011). Congenital hypogonadotropic hypogonadism (CHH) is a rare disorder of sexual maturation characterized by gonadotropin (Gn) deficiency with low sex steroid levels associated with low levels of follicle stimulating hormone (FSH) and luteinizing hormone (LH). "TAC3/TACR3 mutations have been reported in normosmic congenital hypogonadotropic hypogonadism (nCHH) (OMIM #146110)." (PMID 22031817, 2011).
diabetes (1 paper, 2022). "Therefore, the suppression of Kiss1, Tac3, and Pdyn expression in severely diabetic rats 8 weeks after STZ injection observed in the present study might be rapidly induced by STZ administration and might not be a gradual induction in proportion to the severity of diabetes." (PMID 35084363, 2022).
TAC3 also shares sentences with these, for which no sentence is quoted: tumor (6 papers); Anxiety (5); endometriosis (4); Hypertension (4); central precocious puberty (3); intrauterine growth restriction (3); Kallmann syndrome (3); lung carcinoma (3); ovarian dysfunction (3); Parkinson disease (3); androgen excess (2); cancer (2); Delayed puberty (2); gonadotropin deficiencies (2); of puberty (2); uterine fibroids (2); Anosmia (1); astrocytoma (1); benign prostatic hyperplasia (1); carcinoid tumor (1); chronic asthma (1); cocaine dependence (1); colitis (1); congenital adrenal hyperplasia (1); cryptorchidism (1); depression (1); eosinophilia (1); epilepsy (1); female infertility (1); flushes (1).
A further 23 diseases each share a sentence with TAC3 in 1 paper.